ZNF101 (zinc finger protein 101)
Description:
May be involved in transcriptional regulation.
Synonyms: HZF12; DKFZp570I0164
Tractability: PROTAC: ubiquitination databases record sites on it.
Gene: Protein-coding gene on chromosome 19 (19,668,796 to 19,683,509, forward strand). Ensembl gene ENSG00000181896.
Subcellular location: Nucleus
Pathways (Reactome):
Gene expression (Transcription): Generic Transcription Pathway
Gene Ontology:
Molecular function: protein binding; DNA-binding transcription factor activity, RNA polymerase II-specific; RNA polymerase II transcription regulatory region sequence-specific DNA binding
Biological process: regulation of transcription by RNA polymerase II; regulation of DNA-templated transcription
Cellular component: nucleus
Genetic constraint (gnomAD): Loss-of-function variants: 34 observed, 44.4 expected, observed/expected ratio (o/e) 0.77, 90% interval 0.58 to 1.02. The upper end of that interval is the gene's LOEUF score, 1.02, which puts it in group 4 of 6, group 1 being the genes least tolerant of losing a copy. Missense variants: 464 observed, 545.14 expected, observed/expected ratio (o/e) 0.85, 90% interval 0.79 to 0.92. Synonymous variants: 156 observed, 189.83 expected, observed/expected ratio (o/e) 0.82, 90% interval 0.72 to 0.94.
Homologues: Orthologues: chimpanzee ZNF101 (99% identical), macaque ZNF101 (91% identical). Paralogues in human: ZNF709 (53% identical), ZNF14 (51% identical), ZNF433 (50% identical), ZNF700 (48% identical), ZNF791 (48% identical), ZNF44 (47% identical), ZNF443 (47% identical), ZNF823 (47% identical), ZNF878 (47% identical), ZNF799 (46% identical), ZNF441 (45% identical), ZNF442 (45% identical), and 3 more.
Diseases named in the same sentence as ZNF101 in open-access papers:
ZNF101 is named in the same sentence as 8 diseases in open-access papers, as found by Europe PMC text mining. Sharing a sentence is not in itself a finding about the gene and the disease. The quoted sentences say what the papers report.
atherosclerosis (1 paper, 2025). A disease characterized by the build-up of fatty material and calcium deposition in the arterial wall resulting in partial or complete occlusion of the arterial lumen. "The hepatic knockdown of Zfp961, an ortholog of Znf101, reduced lipogenesis and production of triglyceride-rich lipoproteins and atherosclerosis, without causing hepatic lipid accumulation." (PMID 39782688, 2025). "Thus, it is likely that Casz1 and Znf101/Zfp961 are potential targets to modulate plasma lipoproteins and reduce atherosclerosis." (PMID 39782688, 2025). "This study identifies hepatic Znf101/Zfp961 and Casz1 as potential therapeutic targets to alter plasma lipoproteins and reduce atherosclerosis without causing liver steatosis." (PMID 39782688, 2025). "Based on these studies, we speculate that Zfp961/Znf101 and Casz1 can be targeted to modulate plasma LDL and HDL and to reduce atherosclerosis." (PMID 39782688, 2025).
epilepsy (1 paper, 2025). A brain disorder characterized by episodes of abnormally increased neuronal discharge resulting in transient episodes of sensory or motor neurological dysfunction, or psychic dysfunction. "Early identification of high-risk epilepsy patients can help with personalized treatment strategies by detecting expression levels of key genes, including ZNF101 and MAP2K4." (PMID 40520613, 2025). "The results revealed that ZNF101 played an essential role in epilepsy and was the closest to the cut-off value (cut-off value = 0.60)." (PMID 40520613, 2025). "According to the ROC curves, the expression level of key genes including CTSD, CREG1, PECAM1, ZNF101, RRM2B, MARCKSL1, and MAP2K4 demonstrated a certain accuracy in classifying epilepsy and control groups (0.7 < AUC < 0.9)." (PMID 40520613, 2025). "ZNF101 may influence neuronal survival by regulating DNA repair or apoptosis, while MAP2K4 is involved in the pathogenesis of epilepsy by affecting apoptosis and inflammation through the MAPK signaling pathway." (PMID 40520613, 2025). "Notably, ZNF101 and MAP2K4 significantly contribute to epilepsy diagnosis." (PMID 40520613, 2025).
hepatoma (1 paper, 2025). "We provide evidence that miR-541-3p concurrently reduces apoB and increases apoA1 in human hepatoma cells by regulating 2 different TFs, Casz1 and Znf101." (PMID 39782688, 2025).
Hypertension (1 paper, 2025). The presence of chronic increased pressure in the systemic arterial system. "Research has shown a significant association between the ZNF101 rs2304130 and hypertension." (PMID 39854379, 2025). "Six genes (PTGS2, TBXA2R, ZNF101, KCNJ2, MSRA, and CMTM5) have been reported to be associated with hypertension." (PMID 39854379, 2025).
ZNF101 also shares sentences with these, for which no sentence is quoted: Alzheimer disease (1 paper); breast carcinoma (1); liver steatosis (1); Tics (1).